REN (renin)
Diseases named in the same sentence as REN in open-access papers (continued):
Sharing a sentence is not in itself a finding about the gene and the disease.
Hypertension (continued). "The use of agents acting on the renin-angiotensin-aldosterone system increased in all subgroups (hypertension only intervention patients OR 1.19 (1.06, 1.34; p = 0.004) and controls OR 1.24 (1.15, 1.34; p < 0.0001)." (PMID 21849037, 2011). "The patients experience symptoms related to hypertension and hypokalemia due to renin-secretion by the tumor." (PMID 21871063, 2011). "For instance, androgen receptor blockade (flutamide) significantly attenuated the development of hypertension in females and reduced plasma renin activity and rat renin mRNA in the kidney." (PMID 21603136, 2011). "Thus, in SHRSP renal damage seems to be caused by an arterial hypertension, obviously evoked by disturbed interactions between prostaglandins and the adrenergic nerve system, genetic dysregulation of the renin-angiotensin system, occurrence of vascular wall renin and elevated plasma renin activity." (PMID 22031827, 2011). "Clinically, this tumor is characterized by hypertension, hyperaldosteronism and hypokalemia secondary to excessive renin secretion by tumor cells." (PMID 21871063, 2011). "Hypothetically, if a loss-of-function miRSNP occurred in the AGTR1, ACE, AGT, REN, or ATP6AP2 gene, an increased incidence of hypertension, cardiac/vascular remodeling, and atherosclerosis would be observed." (PMID 20948563, 2010). "Hypertension is believed to result from renin-angiotensin-aldosterone activation triggered by renal hypoperfusion and microvascular ischemia." (PMID 20694451, 2010). "This approach is particularly important in patients of African origin, who are more likely to have low-renin hypertension." (PMID 21532778, 2010). "Mice lacking vitamin D receptor (VDR) have elevated production of renin and angiotensin II, leading to hypertension, cardiac hypertrophy, and increased water intake." (PMID 20049157, 2010). "Decreased renal perfusion as a result of arterial narrowing can additionally lead to juxtaglomerular apparatus (JGA) hyperplasia and renin secretion, resulting in accelerated hypertension and progressive renal injury." (PMID 20981312, 2010). "Estrogen retards the progression of hypertension, delays or attenuates the development of cardiac hypertrophy, limits fibrosis, and reduces the activation of the renin-angiotensin system in salt-sensitive experimental models and in humans." (PMID 21082029, 2010). "Hypertension develops through increased chemokine and cytokine expression, induction of the renin-angiotensin system and increased vascular C-reactive protein (CRP) expression." (PMID 20222993, 2010). "Hypertension with hypokalemia and suppressed renin is known as mineralocorticoid hypertension, the mineralocorticoid involved being aldosterone in the vast majority of cases." (PMID 20482833, 2010). "Hypertension is common among diabetics and has the same pathogenetic mechanisms as insulin resistance, in which the activated renin–angiotensin system contributes to the increased high blood pressure and hyperglycemia." (PMID 20664687, 2010). "Sugar-induced hypertension involves not only the sympathetic nervous system and the renin-angiotensin overactivity, but also hyperinsulinemia and insulin resistance." (PMID 20804606, 2010). "Hypertension develops by several mechanisms, including excessive renin concentrations which lead to activation of the renin-angiotensin system, increased vascular sensitivity to catecholamine, and increased concentrations of aldosterone." (PMID 21070672, 2010). "Hypertension can be broadly classified as "high renin" or "low renin" based on the vasoconstriction-volume (renin/sodium) model of hypertension." (PMID 27713329, 2010). "Renin-producing cells have been the object of intense research efforts for the past fifty years within the field of hypertension." (PMID 20948562, 2010). "In patients with unilateral stenosis, renin-angiotensin mediated vasoconstriction is the primary mechanism of hypertension." (PMID 20591148, 2010).
Hypertension (continued). "Renin-sodium profiling in patients with essential hypertension shows that the plasma renin activity (PRA) is increased in 15 percent, normal in 60 percent, and reduced in approximately 25 percent." (PMID 27713329, 2010). "Patients with essential hypertension and low renin hypertension excrete lower urinary kallikrein than that of normal subjects." (PMID 27713243, 2010). "The benicial effects of renin inhibition on organ damage are partially due to the suppression of hypertension." (PMID 19390623, 2009). "Aliskiren is the first orally bioavailable direct renin inhibitor approved for the treatment of hypertension." (PMID 27713228, 2009). "An ambitious plan of primary and secondary prevention trials has begun in order to demonstrate possible advantages of the treatment with aliskiren alone or in combination with other renin-angiotensin blockers in patients with hypertension." (PMID 19390623, 2009). "Increased RAS activity results in systemic hypertension and expression of ectopic anti-renin or anti-angiotensin molecules decreases hypertension." (PMID 19436702, 2009). "In rats and humans, mutations of the alpha-adducin subunit lead to the stimulation of Na(+), K(+)-ATP-ase activity in renal tubular cells, increased renal Na(+) reabsorption and, subsequently, low-renin hypertension." (PMID 19274077, 2009). "The effects of the direct renin inhibitor aliskiren were compared with losartan in patients with hypertension and left ventricular hypertrophy." (PMID 27713228, 2009). "The evidence supporting the use of renin inhibitors to control hypertension, but limiting this use in patients with kidney disease progression even if ACE and ARB decrease cardiovascular risk in patients with chronic kidney disease." (PMID 27713228, 2009). "Comparative effects of aliskiren-based and ACE-based therapy on the renin system during long-term (6 months) treatment and withdrawal in patients with hypertension were compared in some study." (PMID 27713228, 2009). "The renin-angiotensin-aldosterone system (RAAS) plays a dominant role in the pathophysiology of hypertension, diabetes mellitus, chronic kidney disease and chronic heart failure." (PMID 27713228, 2009). "The beneficial effects of the renin-angiotensin pharmacological inhibition have been also observed in animal models of hypertension." (PMID 19390623, 2009). "The renin-angiotensin-aldosterone system (RAS) cascade is a major target for the clinical management of hypertension." (PMID 18582379, 2008). "Recently, transgenic rodent models have been developed that over express both human REN and angiotensinogen, which leads to hypertension via chronic overproduction of Ang II." (PMID 17641732, 2007). "The Tsukuba hypertensive mice (THM), which express the human REN and angiotensinogen genes, have been provento develop hypertension." (PMID 17641732, 2007). "Commonly occurring ENaC variants, including intronic substitution (i12-17CT) were found associated with an increased urinary potassium excretion rate in relation to the renin levels as well as with hypertension in humans." (PMID 17592634, 2007). "There is on going debate on the topic of the aldosterone: renin ratio and its role, if any, in subjects with hypertension." (PMID 17490489, 2007). "The genetically hypertensive SHR is a renin-angiotensin system-dependent model of hypertension that also exhibits oxidative stress and disrupted endothelial NOS (eNOS) activity." (PMID 17986358, 2007). "These rare forms of hypertension are further characterized by extreme salt sensitivity and suppressed P-renin." (PMID 17487281, 2007). "A high aldosterone: renin ratio has been found in 15% of a UK hypertension clinic and the general community." (PMID 17490489, 2007). "Hypertensive mice that express the human renin and angiotensinogen genes are used as a model for human hypertension because they develop hypertension secondary to increased renin-angiotensin system activity." (PMID 17641732, 2007).
Hypertension (continued). "Comparative gene expression profiling of a resistance artery taken from rats with either renin-angiotensin-dependent or glucocorticoid-induced hypertension has identified over 800 genes showing significant changes." (PMID 17986358, 2007). "In fact, even in cases with unequivocal Liddle's syndrome due to activating ENaC mutations the penetrance of disease phenotype is variable, with inconstant occurrence of hypertension, hypokalemia and suppressed renin levels from patient to patient." (PMID 15661075, 2005). "Hypertension, neural nitric oxide synthase (nNOS) and renin changes were also prevented by maintaining uric acid levels in the normal range with allopurinol or benziodarone (a uricosuric)." (PMID 15507132, 2004). "Moreover, in the development of hypertension, the effect size of renin was significantly different between sexes." (PMID 41598580, 2026). "Renin-angiotensin-aldosterone system inhibitor medication, consisting of angiotensin converting enzyme inhibitors and angiotensin receptor blockers, as well as statins, is used to treat hypertension and hypercholesterolemia, respectively." (PMID 41801622, 2026). "The combination of a beta-blocker and angiotensin-converting enzyme inhibitor (ACEi) acts on two neuroendocrine systems implicated in the pathophysiology of hypertension and multiple CVD: beta-blockers on the sympathetic nervous system and ACEis on the renin-angiotensin system (RAS)." (PMID 42200486, 2026). "After surgery, hypertension, hyperaldosteronism, and low renin activity may be corrected in some patients." (PMID 40815389, 2026). "Additionally, several physiological studies in rat congenital ID promote altered renin–angiotensin signaling and hypertension with maturation, especially in males." (PMID 40220077, 2026). "Calcium supplementation may reduce hypertension as well as excessive uterine muscle contractions, as calcium is known to suppress the renin-angiotensin system and decrease the contraction of vascular smooth muscle cells." (PMID 40416681, 2025). "However, with the diagnosis of a JGCT, it is clear that her renin-mediated hypertension occurred through a separate mechanism with renin-mediated vasoconstriction." (PMID 40546339, 2025). "We suspected that the elevated IAP caused a reduction in renal blood flow with a subsequent decrease in urine production, a rise in serum creatinine and urea, and a significant increase in plasma renin activity levels that eventually led to a hypertensive crisis." (PMID 40538618, 2025). "Hypertension, is one of the most prevalent components of MetS, and exerts significant deleterious effects on blood vessels through the activation of the Renin-Angiotensin System (RAS), ultimately promoting the development and progression of atherosclerosis as previously discussed." (PMID 40969606, 2025). "Together, obesity and hypertension-induced activation of macrophages promotes release of inflammatory cytokines with downstream activation of the sympathetic nervous system and renin-angiotensin-aldosterone system (RAAS) with deleterious effects on BP regulation and renal function." (PMID 40014185, 2025). "The relation between arterial hypertension and COVID-19 as well as the impact of antihypertensive drugs, such as renin–angiotensin–aldosterone system (RAAS) blockers, on SARS-CoV-2 infection and disease severity persist as two debatable topics since the beginning of the pandemic." (PMID 39862311, 2025). "In addition, we also explored the impact of vitamin D deficiency on plasma direct renin, aldosterone, and ARR values in patients with hypertension." (PMID 41048520, 2025). "If a patient presents with new or untreated hypertension, screening should be considered before starting antihypertensive agents that could affect the renin–angiotensin–aldosterone system." (PMID 40113595, 2025). "Additionally, liver dysfunction has been shown to activate the renin-angiotensin-aldosterone system (RAAS), further increasing hypertension risk." (PMID 41282031, 2025).
Hypertension (continued). "Future large-scale, long-term randomized trials, incorporating biomarker-guided strategies, are essential to determine whether renin inhibition can carve a defined role in precision hypertension management." (PMID 41409925, 2025). "However, hypertension induces activation of the vascular wall renin-angiotensin system (RAS) through mechanical stress, facilitating calcium-phosphorus deposition." (PMID 40314886, 2025). "Since the onset of hypertension occurs during childhood in these patients, secondary screening tests such as plasma aldosteronism-to-renin ratio (ARR) test should be done to rule out other causes of hypertension and avoid cardiovascular damage." (PMID 40000975, 2025). "The mechanisms in which obesity causes hypertension arecomplex and include overactivation of the sympathetic nervous system (SNS),stimulation of the renin-angiotensin-aldosterone system, alteration inadipose-derived cytokines, insulin resistance, and structural and functionalrenal changes." (PMID 40927078, 2025). "In contrast, patients with “moderate to high renin” hypertension may display excessive vasoconstriction attributed to renin-angiotensin II activity, thus justifying the prescription of ACEIs/ARBs and β-blockers as preferred treatment options." (PMID 40106408, 2025). "Hypertension is a significant concern among older adults, characterized by complex pathophysiological changes in the cardiovascular system, such as arterial stiffening and alterations in the renin‐angiotensin‐aldosterone system." (PMID 41409536, 2025). "Given the initial assumption that our patient's tumor was very likely malignant, it stood to reason that she could have renin-mediated hypertension from anatomical damage to the renal artery abutting the mass." (PMID 40546339, 2025). "Renin-angiotensin system inhibitors, such as direct renin inhibitors, angiotensin II receptor blockers and angiotensin-converting enzyme inhibitors are frequently used to manage hypertension and heart failure." (PMID 41417371, 2025). "Serum UA levels have been considered a risk factor for kidney injury or atherogenic factors that can cause renal inflammation, oxidative stress, endothelial lesions, and hypertension and activate the renin–angiotensin–aldosterone system (RAAS) to provoke cardiovascular disease or renal disease." (PMID 40710422, 2025). "Through processes including elevated sympathetic activity, compromised endothelial function, and activation of the renin-angiotensin-aldosterone system, IR - which is defined by the decreased cellular absorption of glucose in response to insulin - exacerbates hypertension." (PMID 40255834, 2025). "Elevated cortisol levels, which may be seen in individuals experiencing loneliness, can contribute to hypertension through their effects on the renin-angiotensin system and adrenergic receptors." (PMID 41473723, 2025). "Moreover, visceral obesity is strongly associated with the overactivation of the renin-angiotensin-aldosterone system (RAAS), further promoting hypertension and endothelial dysfunction." (PMID 40839683, 2025). "The renin-angiotensin system (RAS) inhibitors are widely used to treat hypertension." (PMID 38669003, 2025). "Ultimately the differential diagnoses can be excluded when incorporating the clinical presentation of hypertension, elevated renin, aldosterone, and hypokalemia, in addition to the findings of normalized renin and aldosterone levels, and normalized blood pressure levels after removal of the tumor." (PMID 39568313, 2025). "The presence of hypertension and various acute or chronic complications may affect the renin-angiotensin-aldosterone system (RAAS) in patients with type 2 diabetes mellitus (T2DM), which plays a crucial role in the regulation of glucose metabolism." (PMID 40106408, 2025). "We hypothesized that chronic TMAO supplementation modulates hypertension-related complications through alterations in the tissue renin-angiotensin system (RAS)." (PMID 40951831, 2025).
Hypertension (continued). "Additionally, enlarging cysts compress renal vasculature, leading to ischemia and chronic activation of the renin-angiotensin-aldosterone system (RAAS), which underlies the early onset of hypertension in ADPKD." (PMID 40268755, 2025). "Relevant hypertension examinations like renal ultrasound, renal artery ultrasound, and renin–angiotensin system were completed and no obvious causes were found." (PMID 40760521, 2025). "We identified a novel protective recessive association between a missense variant in SGLT4 (rs61746559), a sodium-glucose transporter with a possible role in the renin-angiotensin-aldosterone system, and hypertension (OR = 0.2, p = 3 × 10−8, dominance deviation p = 7 × 10−6)." (PMID 40306283, 2025). "L-NAME hypertension is characterized by increased renin–angiotensin activity and salt sensitivity, inhibiting nitric oxide (NO) production and leading to vasoconstriction, increased peripheral resistance, cardiac hypertrophy, renal damage, and oxidative stress." (PMID 40507134, 2025). "Boolean operators (AND, OR) were used to ensure both sensitivity and specificity, and equivalent Emtree terms were applied for the Embase search (e.g., ‘renin inhibitor’/exp, ‘angiotensin converting enzyme inhibitor’/exp, ‘angiotensin receptor antagonist’/exp, ‘hypertension’/exp)." (PMID 41409925, 2025). "Thirty-seven patients (35.2%) presented arterial hypertension and 38 (36.2%) were receiving renin-angiotensin-aldosterone inhibitors, namely angiotensin-converting enzyme inhibitors (n=24, 22.9%), angiotensin receptor blockers (n=13, 12.4%), and spironolactone (n=1, 1.0%)." (PMID 40161090, 2025). "Given that the PRA level is much higher in patients with MHT than in those with mild-to-moderate hypertension, compensatory activation of renin induced by ARB or ACEI monotherapy can make it difficult to suppress the angiotensin II type 1 receptor (AT1R) adequately in MHT." (PMID 39349898, 2025). "Once installed, MASLD and CKD may worsen insulin resistance, dyslipidemia, and hypertension through inflammation, oxidative stress, uremia, metabolic acidosis, sedentarism, and further activation of the renin–angiotensin–aldosterone system." (PMID 41007724, 2025). "The development of hypertension is complex and involves multiple pathophysiological factors – excessive activation of the renin-angiotensin-aldosterone system (RAAS), increased activity of the sympathetic nervous system, endothelial dysfunction, and also inflammation." (PMID 40454237, 2025). "By synthesizing evidence from RCTs and real-world studies, we seek to provide a comprehensive assessment of clinical, renal, and hemodynamic outcomes, thereby informing clinicians and policymakers on the role of renin inhibitors in contemporary hypertension management." (PMID 41409925, 2025). "Developing arterial hypertension is associated with increased renin-angiotensin system activity while the baroreflex is not impaired." (PMID 40149720, 2025). "This may be the case, for example, when renin-angiotensin system (RAS) inhibitors are already used in patients with a diagnosis of hypertension." (PMID 40423762, 2025). "Type 2 diabetes mellitus (T2DM) patients are often accompanied by hypertension and various acute or chronic complications that may activate or inhibit the renin-angiotensin-aldosterone system (RAAS), leading to increased rates of hospitalization and mortality." (PMID 40106408, 2025). "Moreover, proximal tubular sodium reabsorption is increased, leading to diminished distal sodium delivery and stimulating the macula to increase renin secretion, thereby contributing to the perpetuation of the vicious cycle of hypertension and fluid overload." (PMID 40724891, 2025). "Though the precise and detailed mechanism between RCC and hypertension has not been fully understood, some researchers hypothesized that renin-angiotensin-system might play a potential role." (PMID 40933888, 2025).